JCHAIN (joining chain of multimeric IgA and IgM)
Description:
Serves to link two monomer units of either IgM or IgA. In the case of IgM, the J chain-joined dimer is a nucleating unit for the IgM pentamer, and in the case of IgA it induces dimers and/or larger polymers. It also helps to bind these immunoglobulins to secretory component.
Synonyms: IGCJ; IGJ; JCH
Tractability: Antibody: its Gene Ontology location is reachable by antibodies, with high confidence; UniProt places it where antibodies can reach, with medium confidence; UniProt predicts a signal peptide or a membrane-spanning region. PROTAC: ubiquitination databases record sites on it.
Gene: Protein-coding gene on chromosome 4 (70,655,541 to 70,681,817, reverse strand). Ensembl gene ENSG00000132465.
Subcellular location: Secreted
Pathways (Reactome):
Hemostasis: Cell surface interactions at the vascular wall
Vesicle-mediated transport: Scavenging of heme from plasma
Gene Ontology:
Molecular function: IgA binding; immunoglobulin receptor binding; peptidoglycan binding; phosphatidylcholine binding; protein homodimerization activity; single-stranded DNA binding; antigen binding; protein-macromolecule adaptor activity
Biological process: adaptive immune response; antibacterial humoral response; glomerular filtration; innate immune response; positive regulation of respiratory burst; protein-containing complex assembly; humoral immune response; immune response
Cellular component: blood microparticle; dimeric IgA immunoglobulin complex; extracellular exosome; extracellular region; hexameric IgM immunoglobulin complex; monomeric IgA immunoglobulin complex; pentameric IgM immunoglobulin complex; secretory dimeric IgA immunoglobulin complex; secretory IgA immunoglobulin complex
Genetic constraint (gnomAD): Loss-of-function variants: 2 observed, 6.51 expected, observed/expected ratio (o/e) 0.31, 90% interval 0.12 to 0.97. That is too few expected variants to judge how well the gene tolerates losing a copy. Missense variants: 73 observed, 106.02 expected, observed/expected ratio (o/e) 0.69, 90% interval 0.57 to 0.84. Synonymous variants: 17 observed, 36.66 expected, observed/expected ratio (o/e) 0.46, 90% interval 0.32 to 0.69.
Homologues: Orthologues: chimpanzee JCHAIN (99% identical), macaque JCHAIN (96% identical), dog JCHAIN (82% identical), guinea pig JCHAIN (78% identical), pig JCHAIN (77% identical), mouse Jchain (76% identical), rat Jchain (76% identical), rabbit JCHAIN (71% identical).
Diseases named in the same sentence as JCHAIN in open-access papers:
JCHAIN is named in the same sentence as 61 diseases in open-access papers, as found by Europe PMC text mining. Sharing a sentence is not in itself a finding about the gene and the disease. The quoted sentences say what the papers report.
breast carcinoma (11 papers, 2019 to 2025). "This study found that JCHAIN is a potential diagnostic and prognostic marker in various cancers and is closely related to methylation, cell stemness, and the immune microenvironment in breast cancer." (PMID 41010015, 2025). "Subsequently, we conducted enrichment analyses of JCHAIN using Kyoto Encyclopedia of Genes and Genomes (KEGG) and Gene Set Enrichment Analysis (GSEA) and validated the mechanism by which JCHAIN inhibits breast cancer through in vitro experiments." (PMID 41010015, 2025). "It was previously reported that JCHAIN was involved in breast cancer invasion and metastasis through regulation of the NF-kappa B signalling pathway." (PMID 40999451, 2025). "In general, our research undertakes a comprehensive analysis of JCHAIN as a potential prognostic factor for breast cancer and an indicator of tumor microenvironment reconstruction." (PMID 41153653, 2025). "This study explored the role of JCHAIN in breast cancer, with a focus on its relationship to the tumor microenvironment (TME) and its prognostic significance." (PMID 41153653, 2025). "Afterwards, the function of JCHAIN was analysed by KEGG as well as GSEA, and the function of JCHAIN in breast cancer cells was verified by in vitro experiments." (PMID 41010015, 2025). "Single-cell investigations have revealed that JCHAIN is primarily found in plasma cells and B cells in breast cancer." (PMID 41010015, 2025). "While this study provides novel insights into JCHAIN’s role in breast cancer, several limitations warrant consideration." (PMID 41153653, 2025). "In a cohort study, higher expression of mRNA of the JCHAIN gene was correlated with favorable survival in women with breast cancer of luminal origin and proposed as a possible biomarker." (PMID 39057100, 2024). "In breast cancer, we found that the JCHAIN was negatively correlated with cellular stemness." (PMID 41010015, 2025). "Mechanistically, JCHAIN downregulation in breast cancer involves three interconnected pathways." (PMID 41153653, 2025). "It suggested that JCHAIN may play a key role in breast cancer through the IL2 and JAK-STAT pathways." (PMID 41010015, 2025). "In breast cancer, the JCHAIN inhibits proliferative migration through the NF-KB signalling pathway." (PMID 41010015, 2025). "In contrast, the enrichment of different pathways in the low-expression group of JCHAIN suggests that JCHAIN may have a complex regulatory role in the cell cycle within breast cancer biology." (PMID 41153653, 2025). "Notably, JCHAIN exhibits distinct dysregulation patterns and prognostic roles across malignancies, with its prognostic significance in breast cancer showing both overlaps and contrasts with other tumor types." (PMID 41153653, 2025). "This indicates that JCHAIN may inhibit the proliferation and migration of breast cancer cells by affecting IL-2 and STAT4." (PMID 41010015, 2025). "A study discovered that the JCHAIN may bind to six genes in ductal breast cancer and could be used as a predictive biomarker for the tumour microenvironment." (PMID 41010015, 2025). "JCHAIN mRNA expression was compared between tumor and normal samples in breast cancer." (PMID 41153653, 2025). "In addition, we evaluated the JCHAIN expression and its prognostic role in the 61 pairs of clinical breast cancer tissues." (PMID 41153653, 2025). "In Tamoxifen-treated MCF7 samples, the downregulation of the JCHAIN and C1RL, which are reported by the Human Protein Atlas database to be associated with favourable outcomes in breast cancer, is of concern; however, IGKV-4, which is favourable in breast cancer, was upregulated." (PMID 38233507, 2024). "Moreover, the joining chain of multimeric IgA and IgM (JCHAIN) has been identified as capable of hindering the growth and mobility of breast cancer cells by suppressing NF-κB -mediated EMT." (PMID 39135991, 2024).
breast carcinoma (continued). "The consistently lower JCHAIN mRNA expression in tumor samples compared to normal samples, in conjunction with its association with TNM staging and breast cancer subtypes, strongly suggests that JCHAIN is intricately involved in the biological processes that drive breast cancer progression." (PMID 41153653, 2025). "This study identifies JCHAIN as a novel prognostic biomarker and indicator reflecting immune activity in the tumor microenvironment (TME) in breast cancer." (PMID 41153653, 2025). "Our study constructed the prognostic signature based on breast cancer PD-1/PD-L1 pathway molecular typing-related genes (IFNG, JCHAIN, ELOVL2, PIGR, PAGE5, ACTL8, and CLEC3A)." (PMID 37154982, 2023).
COVID-19 (5 papers, 2021 to 2023). A disease caused by infection with severe acute respiratory syndrome coronavirus 2. "Immunoglobulin-encoding genes were markedly over-expressed in COVID-19 compared to HLTY and INFL, and peaked in OXY1/TUBE EARLY (“hill” pattern, e.g. IGHM, IGHA1, IGHG1, JCHAIN)." (PMID 34135895, 2021). "On the other hand, the Humoral response GO term, reflecting both complement (SERPING1, C1QB) and B cell activation (JCHAIN, POU2AF1), was progressively more enriched in COVID-19 patients from T1 through T3." (PMID 37365222, 2023). "For example, the protein components of human immunoglobulin (JCHAIN and IGKV3D-20) and human hemoglobin proteins (HBB and HBA) were upregulated in COVID-19 patients, suggesting an enhanced immune response and potential bleeding in their intestines." (PMID 35045853, 2022). "Specifically, signatures of plasma cells (IGHG3, IGKC, IGHM, JCHAIN, IGHG2, IGKV4-1, IGLV3-1, IGHA1), activated fibroblasts (COL1A1, COL1A2, COL3A1), inflammatory cytokines (CXCL9, CCL18) and complement factors (C1QB, C1QC) dominated the DE genes for the COVID-19 lung sections." (PMID 37858234, 2023).
acute lymphoblastic leukemia (3 papers, 2016 to 2025). Leukemia with an acute onset, characterized by the presence of lymphoblasts in the bone marrow and the peripheral blood. "JCHAIN encodes the immunoglobulin J chain and links monomer units of IgA and IgM, and the upregulation of JCHAIN was likely related to tumor aggression, as studied in a cohort of patients with acute lymphoblastic leukemia (ALL) who had died." (PMID 33329695, 2020). "In adult Hispanic B-cell acute lymphoblastic leukemia (B-ALL), high JCHAIN expression-part of a 3-gene signature with ID1 and ID3-predicts poor induction therapy response and shortened survival, driven by NF-κB pathway hyperactivation." (PMID 41153653, 2025).
autoimmune disease (3 papers, 2016 to 2024). A disorder resulting from loss of function or tissue destruction of an organ or multiple organs, arising from humoral or cellular immune responses of the individual to their own tissue constituents. "CD24, which carries polymorphisms linked to the progression of autoimmune disorders, and JCHAIN genes were differentially expressed in both AL and CA lesions compared to NAWM for three donors." (PMID 39596026, 2024). "Two transcripts, JCHAIN (IgJ) and TNFRS17, both increased 1.7-fold and with high absolute expression level, have previously been identified as markers of plasmacytoid cells in autoimmune disease." (PMID 38978787, 2024).
multiple myeloma (3 papers, 2021 to 2025). "CD8+ T cells transduced with JCHAIN-specific T cell receptors (TCRs) demonstrated potent in vitro and in vivo killing activity against multiple myeloma, confirming JCHAIN’s potential as an immunotherapeutic target." (PMID 41010015, 2025). "We identified potential biomarkers, including JCHAIN, C1 complex proteins, and others, for multiple myeloma detection." (PMID 37835457, 2023). "immunotherapy for multiple myeloma, JCHAIN emerges as a novel target antigen." (PMID 41010015, 2025). "A plasma proteomics study revealed that JCHAIN could be exploited as a possible biomarker for multiple myeloma." (PMID 41010015, 2025). "The combination of markers, including the complement C1 complex, JCHAIN, and CD5L, resulted in a prediction model with an AUC of 0.96 for the identification of multiple myeloma patients across various cancer patients." (PMID 37835457, 2023). "Using differential expression analysis and machine learning, the complement C1 complex, JCHAIN, and CD5L were identified as potential biomarkers for diagnosing multiple myeloma (MM)." (PMID 37835457, 2023). "These markers, including the complement C1 complex, JCHAIN, and CD5L, were combined in a prediction model with high accuracy for identifying multiple myeloma patients." (PMID 37835457, 2023).
hepatocellular carcinoma (2 papers, 2019 to 2025). A malignant tumor that arises from hepatocytes. "In a study conducted on H22 hepatocellular carcinoma-bearing mice, it was discovered that the ethyl acetate extract of Streptococcus mongolicus exerts antitumour effects by enhancing JCHAIN protein expression." (PMID 41010015, 2025).
influenza (2 papers, 2022 to 2025). An acute viral infection of the respiratory tract, occurring in isolated cases, in epidemics, or in pandemics; it is caused by serologically different strains of viruses (influenzaviruses) designated A, B, and C, has a 3-day incubation period, and usually lasts for 3 to 10 days. "The observed increase in JCHAIN expression could indicate a late-phase immune response, resulting in sustained antibody production and improved maternal and fetal influenza protection." (PMID 40332395, 2025).
intrahepatic cholangiocarcinoma (2 papers, 2025). A carcinoma that arises from the intrahepatic bile duct epithelium in any site of the intrahepatic biliary tree. "In intrahepatic cholangiocarcinoma (ICC), JCHAIN is a core marker of the “plasma cell+” immune infiltration pattern (co-expressed with IGHG1), which correlates with favorable overall survival by enhancing anti-tumor immunity." (PMID 41153653, 2025). "Concurrently, in intrahepatic cholangiocarcinoma (ICC), plasma cells characterised by IGHG1 and JCHAIN, alongside immune cell infiltration, portend improved survival rates." (PMID 41010015, 2025).
Bladder Urothelial Carcinoma (1 paper, 2025). "The relationship between DFI and JCHAIN expression was later investigated, and it was discovered that high JCHAIN expression in Bladder Urothelial Carcinoma (BLCA), CHOL, COAD, Brain Lower Grade Glioma (LGG), LIHC, and UCEC was associated with good DFI." (PMID 41010015, 2025).
breast tumors (1 paper, 2025). "JCHAIN protein expression was decreased in breast tumors compared to normal tissues." (PMID 41153653, 2025).
cervical squamous cell carcinoma (1 paper, 2025). A squamous cell carcinoma arising from the cervical epithelium. "In disease-specific survival analysis, increased JCHAIN expression in BRCA, Cervical Squamous Cell Carcinoma and Endocervical Adenocarcinoma (CESC), HNSC, LUAD, and SKCM resulted in good DSS, whereas the inverse was true in GBM and Uveal Melanoma (UVM)." (PMID 41010015, 2025).
Crohn disease (1 paper, 2024). A gastrointestinal disorder characterized by chronic inflammation involving all layers of the intestinal wall, noncaseating granulomas affecting the intestinal wall and regional lymph nodes, and transmural fibrosis. "For instance, three markers JCHAIN/IgJ, IGLL5 and MZB1, which are strong markers for B-cells, are also markers of plasmacytoid cells in Crohn's Disease mesenteric adipose fat." (PMID 38978787, 2024).
endometrial carcinoma (1 paper, 2025). A malignant tumor arising from the epithelium that lines the cavity of the uterine body. "In endometrial carcinoma, a positive correlation between CXCL9 and JCHAIN was observed, with JCHAIN promoting cytotoxic function." (PMID 41010015, 2025).
epilepsy (1 paper, 2025). A brain disorder characterized by episodes of abnormally increased neuronal discharge resulting in transient episodes of sensory or motor neurological dysfunction, or psychic dysfunction. "Among them, we observed that the levels of CD3D, CD3G, CTSW, and JCHAIN were all significantly downregulated in epilepsy samples in the GSE143272 and GSE32534 datasets." (PMID 40697415, 2025). "Integrated transcriptomic and single-cell sequencing analyses identified CD3D, CD3G, CTSW, and JCHAIN as the key epilepsy genes that were also closely related to T cell function." (PMID 40697415, 2025). "JCHAIN was high-expressed in B cells, suggesting that B cells and antibody-mediated immune responses may influence the progression and severity of epilepsy." (PMID 40697415, 2025). "A total of nine hub genes were screened in this study, in particular, four hub genes (CD3D, CD3G, CTSW, and JCHAIN) could effectively distinguish epilepsy samples." (PMID 40697415, 2025). "CD3D, CD3G, CTSW, and JCHAIN were consistently expressed in the GSE143272 and GSE32534 datasets and all showed a low expression in epilepsy samples." (PMID 40697415, 2025). "Second, the specific mechanism of the roles of CD3D, CD3G, CTSW, and JCHAIN in the development of epilepsy has not been verified by cell or animal experiments." (PMID 40697415, 2025).
glioblastoma (1 paper, 2025). The most malignant astrocytic tumor (WHO grade IV). "Our analysis revealed that JCHAIN is downregulated in most tumours yet highly expressed in glioblastoma multiforme (GBM) and uveal melanoma (UVM)." (PMID 41010015, 2025).
liver fibrosis (1 paper, 2022). "The CKG automatically reproduced our previous results showing dysregulation of proteins involved in immune system regulation and inflammation, such as C7, JCHAIN, PIGR and A2M, a known marker of liver fibrosis for which CKG reported 14 publications, confirming this connection." (PMID 35102292, 2022).
lung carcinoma (1 paper, 2025). "The JCHAIN amplification occurred in the majority of malignancies, including BLCA, Non-Small Cell Lung Cancer, PAAD, BRCA, OV, ESCA, SKCM, Sarcoma (SARC), Lung Cancer, ESCA, KIRC, LIHC, and TGCT." (PMID 41010015, 2025).
mastitis (1 paper, 2024). Inflammation of breast tissue during lactation or postpartum due to an obstructed duct or infection. "The highest known upregulated gene in Northern Finncattle females was JCHAIN, associated with mastitis response." (PMID 39333243, 2024).
prostate carcinoma (1 paper, 2019). A carcinoma that arises from epithelial cells of the prostate gland. "JCHAIN is involved in innate and adaptive immune response, and is differentially expressed in different cancer types (e.g., colon and prostate cancer)." (PMID 30857150, 2019).
Sepsis (1 paper, 2025). Sepsis is defined as life-threatening organ dysfunction caused by a dysregulated host response to infection. "Genes related to the clonal expansion and differentiation of B cells intoimmunoglobulin-secreting cells ( JCHAIN and the IGKVfamily) were upregulated in patients with sepsis, indicating that MKs participate in immune response regulation." (PMID 40443348, 2025).
triple-negative breast carcinoma (1 paper, 2025). An invasive breast carcinoma which is negative for expression of estrogen receptor (ER), progesterone receptor (PR), and human epidermal growth factor receptor 2 (HER2). "JCHAIN was identified as a critical mediator of immune-stromal interactions, particularly in luminal B and triple-negative breast cancer subtypes." (PMID 41153653, 2025).